BRAF (B-Raf proto-oncogene, serine/threonine kinase)
Diseases named in the same sentence as BRAF in open-access papers (continued):
Sharing a sentence is not in itself a finding about the gene and the disease.
cutaneous melanoma (continued). "Taking into account results from cutaneous melanoma studies, the minority of MMHN patients with driver mutations of oncogenes could benefit from KIT and BRAF inhibitors." (PMID 27737700, 2016). "We present herein a validated quantification of mutated BRAF in a large series of human skin melanoma samples, and demonstrate that several cases are not heterozygous." (PMID 26141748, 2015). "Notably, common BRAF and NRAS mutations in cutaneous melanoma are associated with increased miR-21 expression." (PMID 26116372, 2015). "The cytotoxic effects of bromodomain inhibition reported in cutaneous melanoma cells were independent of the mutational status of BRAF or NRAS." (PMID 26397223, 2015). "Approximately 60% of human cutaneous melanomas possess activating mutations in the cytoplasmic kinase BRAF whereas these mutations are not found in the canine disease." (PMID 25022346, 2014). "Skin melanoma patients without signs of chronic sun-induced damage are prone to have mutations in the BRAF or NRAS gene Breast cancer and colon cancer have been found to be more aggressive in patients with low SES and in minority groups." (PMID 22957007, 2012). "Also, the mechanisms of activation of MAPK-pathway in uveal melanoma appear to be distinct from cutaneous melanoma, as mutations in NRAS or BRAF are rarely found." (PMID 23226204, 2012). "The lack of BRAF mutations in posterior UM predicates that missense mutations of BRAF is not related to the unlimited cell proliferation in UM, which is differnt from the pathogenesis of cutaneous melanoma." (PMID 21305041, 2011). "Mutations in BRAF (one of the three rapidly growing fibrosarcoma (RAF) genes in humans; the other two being ARAF and CRAF) occur in ∼2% of human cancers, and are particularly prevalent in cutaneous melanomas (∼50% of cases)." (PMID 20667740, 2010). "Although more sensitive techniques including the ligase detection assay and high amplicon melting PCR have been used to identify the BRAF mutation in other tissues including cutaneous melanoma they have not been applied to uveal melanoma." (PMID 18985043, 2008). "The introduction of BRAF inhibitors like vemurafenib and dabrafenib, often used together with MEK inhibitors such as trametinib has significantly improved outcomes for patients carrying activating MAPK pathway mutations found in roughly 40–60% of cutaneous melanomas." (PMID 41599391, 2026). "In the skin cutaneous melanoma (SKCM) dataset, we observed that dabrafenib achieved a higher predictive ranking in the sample with the BRAF V600E mutation (GSM6022253) and a slightly lower predictive performance in the sample with the BRAF R178* mutation (GSM6022255)." (PMID 39560158, 2025). "Hotspot mutations predominantly in the V600 codon of BRAF and the Q61 codon of NRAS, as well as loss-of-function events in NF1, led to a cascade of perturbations causing upregulation of the MAPK pathway, the most deregulated signalling pathway in cutaneous melanoma." (PMID 38201222, 2023). "In addition, cutaneous melanoma wasfound in a BRAF-positive patient." (PMID 35544941, 2023). "However, because of the positive clinical response of BRAF-positive metastatic cutaneous melanomas to BRAF and MEK inhibitor therapy, these treatments may be considered potential targets in NUM treatment." (PMID 36980308, 2023). "Furthermore, the authors indicated that the common BRAF mutation (present in cutaneous malignant melanoma) was not present in the analyzed cases of PMME." (PMID 35954389, 2022). "The current guidelines for the treatment of cutaneous melanoma include: (A) immunotherapy drugs (immune checkpoint inhibitors) such as pembrolizumab (Keytruda) or nivolumab (Opdivo) as the first drugs tried, especially in tumors without BRAF gene mutation." (PMID 36407184, 2022).
cutaneous melanoma (continued). "However, the genetic alterations that give rise to uveal melanoma (i.e., GNAQ) differ from those in cutaneous melanoma (i.e., BRAF, CDKN2A, CDK4), suggesting that different pathways may be involved in their progression." (PMID 35525274, 2022). "First, in cutaneous melanoma samples from TCGA and GEO, the differentiation of samples with or without resistance to targeted therapy and immune therapy was not considered, nor were BRAF/NRAS mutations in patient tumors." (PMID 36713580, 2022). "The clear similarities between UVR-driven cutaneous melanoma and UVR-associated mucosal melanoma suggest that mucosal melanoma patients with SBS7v2 predominance may benefit from BRAF/MEK inhibitor combinations and from immunotherapies in both the advanced and adjuvant settings." (PMID 33431815, 2021). "However, we found that DDR1 and BRAF are co-expressed in the majority of skin melanoma samples (80%) regardless of BRAF mutational status." (PMID 33014862, 2020). "Unlike skin melanomas, BRAF mutations are extremely rare in uveal melanomas, where the vast majority show mutations in the genes GNAQ and GNA11 that activate the mitogen-activated protein kinase (MAPK) pathway and, consequently, result in increased cell proliferation." (PMID 32911759, 2020). "Interestingly, HSP90 is required for folding of a protein product of mutated BRAF, whereas wild-type BRAF is not stabilized by HSP90 in cutaneous melanoma cells." (PMID 31659567, 2020). "Interestingly, uveal melanoma driver mutations in GNAQ/GNA11 were identified for a decade, but their discovery did not lead to mutation-specific drug development, unlike it the case for BRAF mutations in cutaneous melanoma which saw enormous success." (PMID 32532044, 2020). "Thus, as patients with BRAF-mutant cutaneous melanoma are successfully treated with combined BRAF/MEK inhibitors, it can be hypothesized that CjM patients might also benefit from these agents." (PMID 31683701, 2019). "Furthermore, similar to the findings in melanocytic nevi and cutaneous melanoma, we report that BRAF mutations do not determine the tumor's ERK phosphorylation status." (PMID 28938534, 2017). "While BRAF and NRAS mutation are the most two common mutations in cutaneous melanoma, BAP1 mutation frequently occurs in uveal melanomas exclusively with BRAF or NRAS mutations 146, suggesting that BAP1 mutation may be a specific genetic marker for uveal melanoma." (PMID 28544818, 2017). "Of 8 MTF cultured populations examined, 5 contained activating BRAF mutations (all 5 had the V600K mutation, 2 samples contained V600K and V600E mutations, and 1 also contained the V600E2 mutation (this percentage reflects the prevalence of BRAF activating mutations in cutaneous melanoma patients)." (PMID 26267609, 2015). "Moreover, UM cannot benefit from target therapy tailored for cutaneous melanoma, as BRAF inhibitors, because of the absence of the target mutation and, for reasons yet to be explored, response to new immunotherapies is poorer than for cutaneous melanoma." (PMID 25780931, 2015). "This benefit mostly manifested as stabilization of disease (in contrast to the rapid-onset major tumor regressions seen with mutant-BRAF inhibitors in cutaneous melanoma) raising the speculation that it may have been mediated by mechanisms other than inhibition of the MAPK-pathway." (PMID 23226204, 2012). "In addition, BRAF mutations, commonly found in cutaneous melanomas, are absent from clear cell sarcomas." (PMID 16092965, 2005). "Moreover, differences in the relative importance of aetiological factors between the two tumour types are reflected at the molecular level – activating mutations of BRAF are almost universal in cutaneous melanomas but not in uveal tumours." (PMID 14612910, 2003).
cutaneous melanoma (continued). "Cutaneous melanoma (CM) is genetically heterogeneous and classified into four major subtypes—BRAF-mutant, RAS-mutant, NF1-mutant, and triple wildtype (BRAF/RAS/NF1 wildtype)—with the latter often harboring KIT or GNAQ/GNA11 mutations." (PMID 40565936, 2025). "For the survival analyses, we included patients with a cutaneous melanoma or MUP, treated with the approved anti-PD1 and BRAF/MEKi drugs (n = 257)." (PMID 38473216, 2024). "The majority were cutaneous melanomas (90.9%) and the relapses were most commonly preceded by adjuvant anti-PD1 (76.2%), anti-CTLA4 (11.8%), or BRAF/MEKi (7%)." (PMID 38473216, 2024). "For the survival analyses, we included patients with a cutaneous melanoma or MUP treated with anti-PD1, anti-CTLA4/PD1, and BRAF/MEKi (n = 101)." (PMID 38473216, 2024). "BRAF and RAS are the most common alterations in cutaneous melanoma, and specific inhibitors have shown significant survival benefits." (PMID 38254853, 2024). "Aberrations in kinases such as proto-oncogene BRAF (exons 11 and 15; p.V600E), NRAS (exons 2 and 3; codons 12, 13, and 61), or KIT (exons 11, 13, 17, and 18) are key factors in human skin melanomas, regulating melanocyte proliferation survival and apoptosis." (PMID 38397192, 2024). "Recently, targeted therapies, including inhibitors of c-KIT, NRAS/MEK or BRAF, and immunotherapies, including anti-CTLA-4 and anti-PD-1/PD-L1 antibodies, have revolutionized the treatment of cutaneous melanoma." (PMID 38326751, 2024). "More recently, targeted therapy (e.g. BRAF-inhibitors) and immunotherapy (e.g. anti CTLA-4 and anti-PD-1 antibodies) have greatly influenced the management of (metastatic) cutaneous melanoma." (PMID 38761218, 2024). "Over the last decade, the introduction of BRAF/MEK‐TT and ICI has revolutionized the treatment landscape of cutaneous melanoma, dramatically improving patient outcomes." (PMID 36967556, 2023). "Interestingly, a study showed that RAC1P29S, a common mutation in human cutaneous melanoma, drives BRAFi resistance through an SRF/MRTF program, which suppresses melanocytic differentiation, induces a mesenchymal-like phenotype and increases survival and resistance to BRAF inhibitor." (PMID 36774337, 2023). "Mucosal melanoma (MM) is a very rare and aggressive type of cancer for which immunotherapy or targeted therapy such as BRAF/MEK inhibitors, used in cutaneous melanoma, usually fail." (PMID 37679999, 2023). "Blocking ERK activation rescued IFNγ-mediated apoptosis in 17 of 23 (~ 74%) cell lines representing BRAF, NRAS, NF1 mutant, and triple wild type subtypes of cutaneous melanoma." (PMID 37803324, 2023). "Ten years after transplantation, he was diagnosed with cutaneous melanoma arising from the nasal dorsum and left cervical lymph node metastases with extracapsular extension, stage IIIC (BRAF/NRAS/c-kit wildtype)." (PMID 36941274, 2023). "BRAF (vemurafenib, dabrafenib, encorafenib) and MEK (trametinib, cobimetinib) inhibitors have been well studied for the treatment of cutaneous melanomas, with limited data for the treatment of acral melanoma (NUM specifically)." (PMID 36980308, 2023). "In addition, we found that skin melanomas are significantly enriched in the “naive T-cell”, “effector memory T-cell”, “exhausted T-cell”, “resting Treg T-cell” and “Th1-like” signatures, irrespective of their BRAF, NF1 and RAS mutational status." (PMID 36389735, 2022). "Overall, alterations in BRAF, NRAS, NF1 and KIT are present in 93% of human cutaneous melanomas in a mutually exclusive pattern, although a small fraction of tumors harbor alterations in several of these genes." (PMID 35234863, 2022). "The major subtype is cutaneous melanoma (CM), which usually accompanies the BRAF(v-raf murine sarcoma viral oncogene homolog B1), RAS (Rat sarcoma virus), NF1(Neurofibromatosis 1), and TWT(triple wild-type) mutations." (PMID 35837089, 2022).
cutaneous melanoma (continued). "TCGA samples were thus filtered based on cancer type (Skin Cutaneous Melanoma, SKCM), stage (metastatic), and genomic subtype (BRAF wild type)." (PMID 35805902, 2022). "Combination therapy with BRAF and MEK inhibitors has led to significantly improved OS and progression-free survival (PFS) in advanced cutaneous melanoma." (PMID 35640549, 2022). "The first patient was treated with the combination of Vemurafenib and Cobimetinib, BRAF and MEK inhibitors, respectively, for a cutaneous melanoma." (PMID 32783159, 2021). "The highly activated MAPK signaling pathway results from alterations of the BRAF and NRAS genes is the key driver for the development and progression of the majority of cutaneous melanoma." (PMID 34222023, 2021). "As an example, based on exome and genome sequencing studies, the TCGA Network has classified cutaneous melanoma into four distinct molecular subtypes: BRAF-mutant, NRAS-mutant, NF1-mutant, and BRAF/NRAS/NF1 wild-type (triple-wild-type group)." (PMID 34123788, 2021). "In cutaneous melanoma, immune checkpoint inhibitors anti-CTLA4 and anti-PD1 and targeted therapies against BRAF and MEK have increased the overall survival." (PMID 33585548, 2020). "Whereas cutaneous melanoma is characterized by a UV-mediated high mutation burden and a high incidence of activating mutations in the BRAF protein, uveal melanoma carries a low mutational burden, no UV mutation signature, and a rare occurrence of BRAF mutations." (PMID 32823698, 2020). "Treatment options for patients with advanced cutaneous melanoma expanded significantly with FDA approval of immune-checkpoint blockade drugs and BRAF/MEK targeting signal transduction inhibitors." (PMID 32764384, 2020). "There is no standard oncological treatment available for metastatic UM patients, and BRAF/MEK and immune checkpoint inhibitors show disappointing results when compared to cutaneous melanoma (CM)." (PMID 31200439, 2019). "In 17% (N = 4) of the patients with cutaneous melanoma, prior treatment was recorded and consisted of targeted therapy with BRAF and MEK inhibitors (33% of BRAF mutant patients; N = 4)." (PMID 29988983, 2018). "The PI3K/AKT signal transduction pathway is considered a potential co-target for BRAF and NRAS mutant cutaneous melanoma." (PMID 28938534, 2017). "The role of BRAF and CRAF kinases in NRAS-induced cutaneous melanoma was assessed by inactivating Raf genes in the Tyr::NRASQ61K/o;Ink4a+/− transgenic mouse model." (PMID 28497782, 2017). "Treatment of MEKi combined with AKTi has been used to treat BRAF-mutant, BRAF-WT and NRAS-mutant cutaneous melanoma patients." (PMID 28938534, 2017). "Mutations in v-Raf murine sarcoma viral oncogene homolog B1 (BRAF), NRAS and Kit are among the most prevalent driving aberrations in cutaneous melanoma with 15-20% affecting the NRAS oncogene." (PMID 25277205, 2014). "BRAFV600E mutant cutaneous melanomas are dependent on MAPK signaling for cell-cycle progression and proliferation, and have high sensitivity to type I BRAF inhibitors and to MEK inhibitors." (PMID 22515704, 2012). "For advanced and non-resectable BRAF-mutant cutaneous melanoma, combination BRAF/MEK inhibitors produce high initial response rates and at least a partial objective response in most patients, with only mild toxicity." (PMID 41295253, 2025). "Specifically, we selected dose–response data from the treatment of three BRAF-targeted drugs: i) Dabrafenib, ii) PLX-4720 and iii) SB590885 across multiple cancer cell lines from GDSC1 (comprising only skin cutaneous melanoma (SKCM) cell lines; N = 52) and GDSC2 (N = 279) datasets." (PMID 39304771, 2024). "Unlike cutaneous melanoma, treatments involving immune checkpoint and v-Raf murine sarcoma viral oncogene homolog B1 (BRAF) inhibition have shown limited efficacy in extending survival for those with metastasized uveal melanoma." (PMID 39201396, 2024).
cutaneous melanoma (continued). "These molecular differences explain why CM has benefited from the therapeutic opportunities developed for cutaneous melanoma with anti-BRAF and anti-MEK targeted therapies unlike UM." (PMID 37190299, 2023). "The prognosis of wild-type BRAF cutaneous melanoma (WT Bf-CM) patients remains poor due to the lack of therapeutic options." (PMID 35751033, 2022). "In line with earlier observations in skin melanoma cells, these effects were independent of the mutational status (GNAQ, GNA11, BAP1, BRAF and NRAS) of the UM and CM cell lines." (PMID 34508176, 2022). "The majority (47.6%) of the acral melanoma patients did not exhibit mutations in BRAF, NRAS or NF1, and a substantial portion (28.6% compared to 5.6% in BCH-cutaneous melanoma, p = 2.28e−05) presented a pigmented skin phenotype." (PMID 35840550, 2022). "Meanwhile, this genetic knowledge base of skin melanoma did not turn to the expected wide array of target therapies, except the BRAF inhibitors." (PMID 35628196, 2022). "A recently published retrospective study demonstrated the clinical efficacy and safety of a combination therapy consisting of BRAF and MEK inhibitors (dabrafenib plus trametinib) in Japanese patients with unresectable or metastatic BRAF V600-mutant cutaneous melanoma." (PMID 34504796, 2021). "We report that, consistent with BRN2 playing a key role as a tumor suppressor in melanomagenesis, its locus is frequently lost in human skin cutaneous melanoma (SKCM) metastases, independently of their NRAS or BRAF status, and that BRN2 status contributes to overall patient survival." (PMID 34140478, 2021). "Previous studies have shown that CDKN2A germline PVs does not affect the prevalence of somatic BRAF and NRAS mutations in cutaneous melanomas, and that familial and sporadic melanomas share similar gene expression signatures." (PMID 34069952, 2021). "Regarding tumor characteristics, most patients had cutaneous melanoma (76.8%), were BRAF V600 wild type (74.5%), and had non-central nervous system (CNS) visceral metastases (M1c, 50.3%)." (PMID 34963849, 2021). "It was demonstrated that 17-AAG induced degradation of BRAFV600E and other BRAF mutants, but not wild-type BRAF in cutaneous melanoma cells." (PMID 31659567, 2020). "The BRAF and NRAS proto-oncogene, GTPas genes associated with the MAPK pathway are present in cutaneous melanomas and up to 50% of conjunctival melanomas (unlike other mucosal and intraocular melanomas)." (PMID 30909967, 2019). "Whereas mutant BRAF and NRAS are responsible for the activation of the RAS/RAF/MEK/ERK pathway in most cutaneous melanoma, mutations in these genes are usually absent in UM." (PMID 19568237, 2009). "Randomised prospective trial data support the use of combination ICIs as the first-line treatment for advanced non-resectable cutaneous melanoma, showing improvements in overall survival and progression-free survival compared with patients treated initially with BRAF/MEK inhibitors." (PMID 41295253, 2025). "In the relatively infrequent cases of ALM harboring BRAF mutations, the level of response to BRAF and BRAF-MEK inhibition is similar to BRAF-mutant non-ALM cutaneous melanoma, although the length of response tends to be shorter for ALM than non-ALM cutaneous melanoma." (PMID 38390259, 2024). "Among 104 acral and non-acral cutaneous melanoma cases, we evaluated histological characteristics (acral type, TT, ulceration, and BRAF status), baseline characteristics (gender and age), and treatment options for multivariate analysis to identify relevant prognostic factors for TTR or OS." (PMID 39123482, 2024). "Furthermore, ALM harbors heterogeneity in BRAF mutations, which can be distinct from V600E/V600K, commonly found in non-ALM cutaneous melanoma." (PMID 38390259, 2024).